FGD4 (FYVE, RhoGEF and PH domain containing 4)
Description:
Activates CDC42, a member of the Ras-like family of Rho- and Rac proteins, by exchanging bound GDP for free GTP. Plays a role in regulating the actin cytoskeleton and cell shape. Activates MAPK8 (By similarity).
Synonyms: FRABP; ZFYVE6; frabin; CMT4H
Tractability: PROTAC: ubiquitination databases record sites on it; its protein half-life has been measured.
Safety:
Unwanted effects reported when the protein is acted on. In parentheses: how it was acted on, where the effect was seen, and who reports it.
sensory peripheral neuropathy (source: ClinPGx)
Gene: Protein-coding gene on chromosome 12 (32,399,558 to 32,646,050, forward strand). Ensembl gene ENSG00000139132.
Subcellular location: Cytoplasm, cytoskeleton; Cell projection, filopodium
Subcellular location (Human Protein Atlas): Actin filaments
Pathways (Reactome):
Signal Transduction: CDC42 GTPase cycle; G alpha (12/13) signalling events; NRAGE signals death through JNK
Gene Ontology:
Molecular function: guanyl-nucleotide exchange factor activity; small GTPase binding; metal ion binding
Biological process: actin cytoskeleton organization; cytoskeleton organization; filopodium assembly; regulation of cell shape; regulation of GTPase activity; regulation of small GTPase mediated signal transduction
Cellular component: cytoplasm; cytosol; Golgi apparatus; lamellipodium; ruffle; cytoskeleton; filopodium
Genetic constraint (gnomAD): Loss-of-function variants: 40 observed, 100.57 expected, observed/expected ratio (o/e) 0.4, 90% interval 0.31 to 0.52. The upper end of that interval is the gene's LOEUF score, 0.52, which puts it in group 2 of 6, group 1 being the genes least tolerant of losing a copy. Missense variants: 890 observed, 1,119.7 expected, observed/expected ratio (o/e) 0.79, 90% interval 0.75 to 0.84. Synonymous variants: 376 observed, 389.48 expected, observed/expected ratio (o/e) 0.97, 90% interval 0.89 to 1.05.
Gene-disease validity (ClinGen):
ClinGen rates the evidence that FGD4 causes each of these diseases.
Charcot-Marie-Tooth disease (autosomal recessive): Definitive. An inherited degenerative disorder involving the peripheral nerves.
Homologues: Orthologues: macaque FGD4 (98% identical), chimpanzee FGD4 (97% identical), pig FGD4 (90% identical), dog FGD4 (87% identical), guinea pig FGD4 (81% identical), rabbit FGD4 (81% identical), rat Fgd4 (80% identical), mouse Fgd4 (71% identical), tropical clawed frog fgd4 (59% identical), zebrafish fgd4a (48% identical), zebrafish fgd4b (46% identical), Caenorhabditis elegans exc-5 (20% identical), and 1 more. Paralogues in human: FGD1 (41% identical), FGD2 (36% identical), FGD3 (32% identical), FGD6 (25% identical), FGD5 (22% identical), FARP2 (19% identical), FARP1 (18% identical), ECT2L (12% identical), ARHGEF39 (9% identical), FRMD7 (6% identical).
Diseases named in the same sentence as FGD4 in open-access papers:
FGD4 is named in the same sentence as 33 diseases in open-access papers, as found by Europe PMC text mining. Sharing a sentence is not in itself a finding about the gene and the disease. The quoted sentences say what the papers report.
prostate carcinoma (5 papers, 2016 to 2020). A carcinoma that arises from epithelial cells of the prostate gland. "In our earlier studies, we reported up-regulation of FGD4 expression in Casodex resistant prostate cancer cells, which is possibly the result of loss of expression of miR-17-92a cluster miRNAs in these cells." (PMID 30558664, 2018). "In addition, recent studies have shown that FGD4 expression in prostate cancer clinical samples is significantly up-regulated compared with the normal group, and down-regulation expression of FGD4 in prostate cancer cell lines can cause cell cycle arrest and proliferation reduction." (PMID 32772928, 2020). "In fact, the inhibition of FGD4 expression has been demonstrated to improve drug sensitivity of prostate cancer cells." (PMID 32630240, 2020). "FGD4 overexpression has been observed in pancreatic neuroendocrine neoplasms and expression of FGD4 positively correlates with the aggressive phenotype of prostate cancer." (PMID 32245826, 2020). "Our observations on the involvement of FGD4 in maintaining functional homeostasis of prostate cancer cells suggest its potential for being a suitable therapeutic target." (PMID 30558664, 2018). "Our observation is supported by the TCGA database analysis showing FGD4 DNA copy number amplification and mRNA upregulation in a subset of neuroendocrine prostate cancer and in prostate carcinoma." (PMID 30558664, 2018). "Our results showed the dependence of prostate cancer cells on FGD4 expression for normal functioning, as down regulation of FGD4 reduced cell viability and led to G2/M arrest." (PMID 30558664, 2018). "To confirm the involvement of FGD4 in prostate cancer cell migration, we used the approach of gene overexpression." (PMID 30558664, 2018). "We also confirmed that FGD4 is one of the targets of miR-17 and -20a from this cluster and is upregulated in Casodex resistant prostate cancer cells." (PMID 30558664, 2018). "In this study, we examined the expression of FGD4 in prostate cancer specimens using immunohistochemistry and studied the function of FGD4 in maintaining cell phenotype, behavior and drug sensitivity using overexpression and siRNA-based silencing approaches." (PMID 30558664, 2018). "In this study, we showed that FGD4 expression levels are increased in advanced prostate cancer compared to the luminal cells in benign prostatic hyperplasia." (PMID 30558664, 2018). "Our earlier studies showed an association between ADT, using AR antagonist Casodex, and upregulation of FGD4 in androgen sensitive prostate cancer cells." (PMID 30558664, 2018). "In this study, we provide evidence for the first time that FGD4 expression is upregulated in advanced prostate cancer with higher Gleason Scores and CRPC status." (PMID 30558664, 2018). "If used in treatment of prostate cancer, inhibition of FGD4 would be limited to short-term, localized therapy, compared to the sustained inactivation of FGD4 in Schwann cells of patients with CMT Type 4H, and is unlikely to have the same effects." (PMID 30558664, 2018). "In support of that, we noted a significant decrease (50%) in cell migration in scratch assays and a reduced activation of CDC42 upon inhibition of FGD4 expression in prostate cancer cells." (PMID 30558664, 2018). "Taken together, these observations establish FGD4 as a promoter of migratory behavior of advanced prostate cancer cells." (PMID 30558664, 2018). "In this study, we show a positive correlation of FGD4 expression with aggressiveness of prostate cancer and tumor promoting properties of FGD4 in prostate cancer." (PMID 30558664, 2018). "Nonetheless, our results provide novel information on the association of FGD4 with aggressive prostate cancer and demonstrate a beneficial effect of inhibition of FGD4 in improving the effectiveness of therapeutic agents for both androgen dependent and castration resistant prostate cancer cells." (PMID 30558664, 2018).
prostate carcinoma (continued). "Our data demonstrate a tumor promoting and a cell migratory function of FGD4 in prostate cancer cells and that inhibition of FGD4 expression enhances the response for both androgen-dependent and independent prostate cancer cells towards currently used prostate cancer drugs." (PMID 30558664, 2018). "Our previous studies showed an up regulation of FGD4 in prostate cancer cells exhibiting resistance to Casodex, which could be the result of down regulation of miR-17-92a miRNA cluster expression that targets FGD4 through binding to the seed sequence at the 3’UTR." (PMID 30558664, 2018). "Although the function of CDC42 is well documented, the involvement of CDC42 specific GEF FGD4 in prostate cancer has not been reported." (PMID 30558664, 2018).
breast carcinoma (3 papers, 2012 to 2025). "In addition, it was recently shown that FGD1, which is functionally related to FGD4, is up-regulated in human prostate and breast cancer, and regulates cancer cell invasion by modulating Cdc42 activation in a cell model." (PMID 22589722, 2012). "Furthermore, we observed that variant carriers of GSTP1 rs1138272 and FGD4 rs10771973 had marginally higher rates of health-related benefits than non-carriers after breast cancer diagnosis." (PMID 39302578, 2025).
nasopharyngeal carcinoma (3 papers, 2012 to 2020). A carcinoma arising from the nasopharyngeal epithelium. "It seems that FGD4 is also involved in the tumorigenesis of nasopharyngeal carcinoma due to its activation of CDC42." (PMID 32772928, 2020). "FGD2, for instance, activates CDC42 and has an important paralog, FGD4, which has been found to interact with EBV LMP1 protein to activate CDC42, a mechanism suggested to be implicated in the nasopharyngeal carcinoma tumurogenesis." (PMID 28654678, 2017).
amyotrophic lateral sclerosis (2 papers, 2024). Amyotrophic lateral sclerosis (ALS) is a neurodegenerative disease characterized by progressive muscular paralysis reflecting degeneration of motor neurons in the primary motor cortex, corticospinal tracts, brainstem and spinal cord. "Fgd4 has been identified as a susceptibility gene for amyotrophic lateral sclerosis, and also associated with Charcot–Marie–Tooth disease." (PMID 39100749, 2024).
neuropathies (2 papers, 2020 to 2021). "Older age, hyperglycemia, and obesity or poor nutritional status, such as single-nucleotide polymorphisms (SNPs) in the FGD4, EPHA5, and FZD3 genes and ABCB1 and GSTP1 polymorphisms, have been associated with the development of taxane-related neuropathy." (PMID 33922821, 2021).
prostate tumors (2 papers, 2016 to 2018). "In this study, we monitored the expression pattern of FGD4 protein in prostate tumors using a custom tissue microarray (TMA) and immunohistochemistry." (PMID 30558664, 2018). "We also noted FGD4 overexpression in prostate tumors with higher Gleason scores and in androgen-independent tumors (unpublished observation)." (PMID 27650539, 2016).
alcohol dependence (1 paper, 2012). Physical and psychological dependence on alcohol. "The two relevant genes, LTBP1 and FGD4, may play important roles in the metabolism of alcohol dependence." (PMID 22295116, 2012).
Anisocoria (1 paper, 2016). Anisocoria, or unequal pupil size, may represent a benign physiologic variant or a manifestation of disease. "Furthermore, anisocoria [PMP22, MPZ, MFN2, SH3TC2; FYVE, RhoGEF, and PH domain‐containing protein 4 (FGD4) gene], miosis (PMP22, MPZ) and mydriasis (MPZ) have been described previously." (PMID 27088055, 2016).
benign prostatic hyperplasia (1 paper, 2018). A non-cancerous nodular enlargement of the prostate gland. "Our results show that the expression of FGD4 is upregulated in cancerous prostates compared to the luminal cells in benign prostatic hyperplasia, although the basal cells showed high staining intensities." (PMID 30558664, 2018).
myelodysplastic syndrome (1 paper, 2018). A clonal hematopoietic disorder characterized by dysplasia and ineffective hematopoiesis in one or more of the hematopoietic cell lines. "Another miRNA, miR-155, was associated to reduced FGD4 levels, resulting in impaired neutrophil migration in myelodysplastic syndromes." (PMID 29813068, 2018).
ophthalmoplegia (1 paper, 2025). Weakness or paralysis of at least one of the muscles controlling the movement of the eye. "Interestingly, two out of three patients with pathogenic variants in the FGD4 gene exhibited ptosis without ophthalmoplegia and one had tongue fasciculations." (PMID 39776111, 2025).
sensory ataxia (1 paper, 2025). Any ataxia in which the causes of the disease is a perturbation of the sensory system, leading to its dysfunction. "Other significant clinical clues in demyelinating CMT subtypes included vocal cord paralysis in GDAP1, ophtalmoparesis and tongue fasciculations in FGD4, severe sensory ataxia in PRX, respiratory involvement in MTMR2 and SBF2, similar to previous reports." (PMID 39776111, 2025).
sensory neuropathies (1 paper, 2018). "Expression of FGD4 is altered in patients with heterogeneous hereditary motor and sensory neuropathies as a result of demyelination of peripheral nerves." (PMID 30558664, 2018).
cancer (6 papers, 2012 to 2023). A tumor composed of atypical neoplastic, often pleomorphic cells that invade other tissues. "A role of FGD4 in promotion of cancer cell migration has been reported earlier." (PMID 27650539, 2016). "SAIC also identified many other cancer driver genes within individual chromosomes (ST 3), such as SKIL, CDK4, PIK3CA, PTEN, FGD4, FGFR1." (PMID 22839576, 2012).
tumor (3 papers, 2012 to 2025). "To understand the functions of FGD4 in promotion of tumor cell growth and cell cycle progression we used FGD4 siRNAs for inhibition of FGD4 expression." (PMID 30558664, 2018). "Accordingly, our findings highlight the importance of elucidating the mechanism by which FGD4 and its related proteins are dysregulated in tumor development." (PMID 22589722, 2012). "Importantly, we uncovered a novel mechanism underlying LMP1-mediated Cdc42 activation, showing that LMP1 physically interacts with FGD4, leading to functional consequences associated with NPC tumorigenesis and tumor progression." (PMID 22589722, 2012).
peripheral neuropathy (2 papers, 2012 to 2024). A disorder affecting the peripheral nervous system. "Recently, a clinical GWAS with 1040 patients treated with paclitaxel identified 3 SNPs located in the EPHA5, FGD4 and NDRG1 genes that were associated with peripheral neuropathy." (PMID 23006423, 2012). "A previous GWAS from an ongoing phase III clinical trial, CALGB 40101, identified 3 top SNPs located in the EPHA5, FGD4 and NDRG1 genes that were associated with paclitaxel-induced peripheral neuropathy, although none reached genome-wide significance." (PMID 23006423, 2012).
infection (1 paper, 2012). The state of being infected such as from the introduction of a foreign agent such as serum, vaccine, antigenic substance or organism. "Apart from this, phosphatidylinositol 3-kinase (PI3K) has been linked to the translocation of FGD4 during infection of the enteric parasite Cryptosporidium parvum." (PMID 22589722, 2012).
peripheral nervous system disorder (1 paper, 2023). A disease involving the peripheral nervous system. "Interestingly, the gene LRP12 is involved in the internalization of lipophilic molecules, and FGD4 is known to cause a peripheral nervous system disorder (Charcot–Marie–Tooth disease)." (PMID 37144689, 2023).
FGD4 also shares sentences with these, for which no sentence is quoted: hepatocellular carcinoma (2 papers); Aarskog–Scott syndrome (1); hereditary motor and sensory neuropathy (1); Hyperglycemia (1); lung adenocarcinoma (1); Miosis (1); Mydriasis (1); myopathies (1); neurodevelopmental disorder (1); Obesity (1); ovarian carcinoma (1); pancreatic neuroendocrine neoplasm (1); ptosis (1); small cell carcinoma (1); Vocal cord paralysis (1).